MYC (MYC proto-oncogene, bHLH transcription factor)
Diseases named in the same sentence as MYC in open-access papers (continued):
Sharing a sentence is not in itself a finding about the gene and the disease.
tumor (continued). "Recently, the sirtuin SIRT6 has been shown to inhibit the transcriptional output of both HIF1 and MYC, and to function as a tumor suppressor." (PMID 25085992, 2014). "To assess the activity of AUY922 on the attenuation of transcriptional activity in vivo, we used immunostaining to determine the expression of the c-MYC transgene, which in this tumor model is driven by AR transcription via a probasin promoter." (PMID 25072314, 2014). "We have shown previously that both activating and repressive complexes of MYC can be detected atmost MYC-bound promoters in tumor cells." (PMID 25253726, 2014). "Transcriptional repression by c-MYC of genes blocking tumor growth such as p21 and p27 CKIs is part of its pro tumoral program." (PMID 24657971, 2014). "Further, in vivo assessment of AR expression in MYC-CaP/CR tumor tissue revealed heterogeneous staining for AR within tumors treated with AUY922 as monotherapy or in combination." (PMID 25072314, 2014). "It has been shown that downregulation of MYC leads to cancer cell growth arrest, senescence, enhanced apoptosis, differentiation and/or tumor regression in mouse models of human cancer." (PMID 24859015, 2014). "We studied the series of 336 DLBCL, NOS tumor samples by IHC on the TMAs using antibodies for MYC, BCL2, BCL6 and Ki67." (PMID 25090026, 2014). "Taking into account only the chromosomal bands harboring BCL2-, BCL6-, IGH- and MYC loci, translocations had been detected in 32/46 tumor samples by chromosome banding, while FISH analysis revealed breaks in 30/46 samples." (PMID 24733537, 2014). "Herein, we report identification of a synthetic lethality link between PRKDC and MYC through pooled shRNA screening and demonstrate inhibition of PRKDC preferentially kills MYC-overexpressing tumor cells." (PMID 25495526, 2014). "This is consistent with the notion that MYC overexpression in cells leads to oncogene addiction, a phenomenon where a tumor becomes reliant on a single dominant oncogene for growth and survival." (PMID 25495526, 2014). "As proof of principle, recombinant adeno-associated virus (AAV)-mediated overexpression of miR-26a was recently shown to attenuate primary MYC-driven tumor formation in a transgenic (Tg) mouse model." (PMID 25253996, 2014). "MAX (myc-associated factor X) gene is a tumor suppressor gene that encodes for MAX protein, which is a component of the MYC-MAX-MXD1 complex that regulates cell proliferation, differentiation, and apoptosis." (PMID 24899893, 2014). "MYC amplifications were essentially restricted to Group 3 (only one out of 8 patients had Group 4 tumor), and MYCN amplifications to SHH and Group 4 tumors." (PMID 24791927, 2014). "In fact, all tumours contain the same chromosomal translocations, which culminate in the deregulation of the oncogene c-MYC." (PMID 25364378, 2014). "Not only has MYC been established as a ‘driver’ oncogene capable of initiating tumor formation, it has also been demonstrated that tumors become addicted to MYC and require MYC for tumor maintenance." (PMID 25495526, 2014). "To confirm inhibition of PRKDC preferentially kills SCLC tumor cells with MYC overexpression, we used shRNAs to knockdown PRKDC." (PMID 25495526, 2014). "Provocatively, CD4+ helper T cells were found to be the key immune effector required for oncogene inactivation-induced tumor regression in the conditional MYC-driven T-ALL mouse model." (PMID 25089198, 2014).
tumor (continued). "In this Review, we highlight the importance of HIF1 and MYC in regulating tumor metabolism and their regulation by sirtuins, with a main focus on SIRT6." (PMID 25085992, 2014). "In comparative studies on tumor samples, as well as in vitro and in vivo preclinical investigations, the LCA variant has been associated with over-expression of the oncogene MYC and with aggressive and invasive tumor cell behavior." (PMID 24708907, 2014). "On the other hand, a subset of MBs, and/or a subset of cells within a given tumor, express high levels of MYC and acquire a concomitantly increased JAG2 protein level, which likely alters the fine-tuned NOTCH signaling cascade." (PMID 24708907, 2014). "Compared to MYC/Runx2, the other three tumour sets yielded many more reads, but from a much smaller number of unique RISs, reflecting the presence of highly expanded tumour clones." (PMID 24586197, 2014). "We recently reported the development of a MYC-CaP castrate resistant (MYC-CaP/CR) transplant tumor model, which expresses amplified wild type AR." (PMID 25072314, 2014). "Among cases with available cytogenetic information, 50% (12/26) harbored amplification or rearrangement of the MYC oncogene, a likely driver of neoplasia in these cases." (PMID 23401819, 2013). "We investigated if HDAC inhibition leads to general restoration of known deregulated pathways in rhabdoid tumor cell lines (like MYC- or RB-pathways)." (PMID 23764045, 2013). "Perhaps, most importantly, the classical SMAD4 tumour suppressor deletion and oncogenic MYC gain were both observed within deleted and gained FMCR respectively." (PMID 24367615, 2013). "Among these chosen genes, p21 and p16 are recognized as crucial tumor suppressor genes, whereas BMI1 and c-MYC are important tumor promoting genes that can regulate expression of p21 and p16 as transcriptional factors." (PMID 23342141, 2013). "This allowed the suppression of angiogenesis and subsequent sustained tumour regression upon MYC inactivation." (PMID 23717341, 2013). "The counteraction of MYC-driven activation of rRNA transcription pointed to a possible tumor suppressor function of MTG16." (PMID 23840896, 2013). "MYC expression is often elevated or deregulated in human neoplasms, and seems to be at the crossroad of several important pathways and processes involved in carcinogenesis, being a key event in gastric carcinogenesis." (PMID 23717612, 2013). "The expression level of MYC mRNA was higher in all tumor samples than their paired controls (RQ = 3.39±0.14; range of 1.57–5.18)." (PMID 23717612, 2013). "We were interested in using a conditional system examining metabolic differences upon MYC suppression in a tumor cell background." (PMID 24280108, 2013). "The proto-oncogene MYC is located within this region and several studies among a number of tumor types have demonstrated the insertion of HPV16 DNA within this region." (PMID 24077122, 2013). "Here, we investigated the epigenetic regulation of pluripotency-associated genes NANOG, OCT4, c-MYC, KLF4, and SOX2, and their correlation with gene expression in cancer cell lines and primary tumor samples." (PMID 24023739, 2013). "We have found evidences that MAX is one of the master regulators of tumor progression, possibly by being an additional regulatory step for the availability of MYC:MAX heterodimers to regulate transcription and increase proliferation." (PMID 24349289, 2013). "The inserted HPV DNA led to an overamplification of the MYC proto-oncogene in several tumor cell lines including a penile cancer specific cell line." (PMID 24077122, 2013).
tumor (continued). "The expression data revealed an increased (≥3-fold) expression of transcriptional regulators in HCC-R tumor tissues (MYC (3.72), CTNNB1 (3.19), and MDM2 (4.27))." (PMID 24377043, 2013). "To explore the physiological importance of SCFFBXO28 E3 ligase activity, we measured the effect of ΔF-FBXO28 on tumour cell proliferation and MYC-induced tumourigenesis." (PMID 23776131, 2013). "In several experimental systems, downregulation of c-MYC expression resulted in sustained tumor regression." (PMID 24130880, 2013). "These tumours grew significantly slower, as compared to the control mice injected with MEFs expressing MYC alone." (PMID 23776131, 2013). "They observed that both strains presented impaired lymphoproliferation and delayed tumor onset when co-expressed with a highly active MYC transgene." (PMID 24349289, 2013). "Here, we show a novel COX-independent effect of the NSAID diclofenac on human and murine tumor cells via reduction of MYC, glucose uptake and lactate secretion." (PMID 23874405, 2013). "c-MYC, SRC and YAP1 were expressed in most samples (WT and control rhabdoid tumours) with c-MYC elevated in NCAM+ALDH1+ tumour." (PMID 23239665, 2013). "The fact that many tumors are oncogene-addicted to c-MYC, renders c-MYC a powerful target for anti-tumor therapy." (PMID 24130880, 2013). "Another similarity is shared by the type of tumour that is formed in H-RAS/MYC transgenic mice or in miR-21 transgenic mice." (PMID 23496142, 2013). "MYC DNA amplification in tumor cell lines established from patients previously treated with chemotherapy continued to be associated with shortened survival." (PMID 23820887, 2013). "Second, recent evidence attributed the deregulated miRNA expression to MYC, which is involved in promoting oncogenic miRNAs and repressing tumor suppressor miRNAs." (PMID 24261995, 2013). "Further, Western-blot had confirmed the up-regulation of Oct-4 and c-MYC expression in intermittent hypoxia conditioned tumor cells." (PMID 24305593, 2013). "In a murine xenograft model established with subcutaneous injection of Namalwa cells, dual treatment efficiently blocked tumor growth, inhibited MYC and induced in situ autophagy." (PMID 23866964, 2013). "Except for two SCLCs, the H1184 cell line with MYCL1 amplification and the SM09-011T1 tumor with MYC amplification, amplification of genes defined by 250K SNP arrays was consistently detected by real-time genomic-PCR." (PMID 23716474, 2013). "Treatment of rhabdoid tumor cell line A204 with SAHA upregulates RB- and MYC- target genes and the pluripotency-associated program controlled by EZH2." (PMID 23764045, 2013). "Nevertheless, MYC-dependent tumor cells were dependent on mitochondrial ROS for cell proliferation as mitochondrial targeted antioxidant MVE drastically reduced cell proliferation." (PMID 24280108, 2013). "MYCN, as well as c-MYC, was widely studied as a transcriptional activator leading to the conclusion that up-regulated target genes are responsible for many aspects of the tumor malignancy." (PMID 23482921, 2013). "Based on these results, diclofenac holds potential as a clinically applicable MYC and glycolysis inhibitor supporting established tumor therapies." (PMID 23874405, 2013). "Down-regulation of MYC protein expression in different animal models of human malignancies leads to tumor regression, indicating that MYC proteins represent interesting therapeutic targets." (PMID 23162796, 2012). "Transgenic models have been invaluable for determining the role of MYC in tumor maintenance as well as for investigating potential efficacy of novel therapeutics against MYC-induced cancer." (PMID 22308267, 2012). "We established a cut-off value for classifying tumors as the lowest MYC IHC score that captures all cases with a confirmed MYC translocation (>50% tumor nuclei positive for MYC)." (PMID 22511926, 2012).
tumor (continued). "MYC activation influences genes involved in multiple facets of tumor biology including proliferation, differentiation, apoptosis and metastasis." (PMID 23145106, 2012). "We show that cases of primary DLBCL with >50% MYC-positive tumor nuclei have increased MYC activity as assessed by GSEA and have an inferior overall survival following R-CHOP treatment." (PMID 22511926, 2012). "To further investigate the role of c-MYC in the pro-tumoral activities of TAMs, we exposed BMDMs to conditioned culture medium from tumor cells, an in vitro model that allows characterization of cell autonomous effects." (PMID 23028984, 2012). "By functional network analysis using 383 differentially expressed genes, MYC pathway was identified to be activated in neoplastic disease." (PMID 22545051, 2012). "Cases in which the majority (>50%) of tumor nuclei stained positive for MYC (10 cases) exhibited moderate to strong staining intensity, while cases in which ≤50% of tumor nuclei were MYC positive had dim to moderate staining intensity (46 cases)." (PMID 22511926, 2012). "IHC analysis of 56 primary DLBCL cases revealed a spectrum of total tumor cell nuclei (ranging from 10% to 90%) that stained positive for MYC by manual scoring." (PMID 22511926, 2012). "By analysis of the Pearson correlation method, we observed that the expression levels of BCL2, CCND1, PCNA, PGK1, and VEGFA were correlated with the levels of MYC in the tumor tissues of ccRCC." (PMID 22545051, 2012). "In establishing the precision of our assay over multiple staining runs, we included the primary DLBCL case #9 (a DLBCL with MYC-translocation and 60% of the tumor nuclei positive for MYC staining) as a control." (PMID 22511926, 2012). "The synergistic effect of MYC and BCL-XL or BCL-2 overexpression on tumor development observed here is in agreement with previous observations in transgenic Eμ-MYC/BCL-2-induced B lymphoma." (PMID 22393362, 2012). "For MYC alone, similar results concerning the kinetics of tumor development and the frequencies of myeloid versus lymphoid tumor cells were obtained using BALB/c mice (data not shown)." (PMID 22393362, 2012). "In a subsequent report from the same group, the tumour regression from c-MYC inactivation in OS cells was attributed to the induction of senescence." (PMID 23036272, 2012). "We further explored the mechanisms of PRC2 gene up-regulation in metastatic tumor cells and found up-regulation of E2F genes, MYC targets and down-regulation of tumor suppressor gene E-cadherin targets in lymph node metastasis through GSEA analyses." (PMID 23251464, 2012). "Patients having either a MYC or MYCN amplification in their tumor clearly have a significantly worse outcome compared to cases without amplification." (PMID 22358457, 2012). "In summary, we have generated a new mouse model to investigate the role of c-MYC macrophage expression on tumor development." (PMID 23028984, 2012). "In MYC/BCL-XL or MYC/BCL-2 mice tumor cells in spleen and liver expressed the myeloid marker MPO but not the T-cell markers." (PMID 22393362, 2012). "Possible clinical application of these findings first requires validation of the anti-tumor potential of targeting c-MYC function in TAMs in an animal model." (PMID 23028984, 2012). "We sought to exploit the predictable kinetics of the MYC/DDC tumor model system to determine the relationship of MYC and SIRT1 in vivo." (PMID 23024800, 2012). "Quantification of MYC positive tumor nuclei for each case by two independent pathologists revealed that the staining and the quantification procedure were highly reproducible." (PMID 22511926, 2012). "Gene set enrichment analysis (GSEA) revealed that primary DLBCL cases with >50% MYC-positive tumor nuclei exhibited coordinate upregulation of MYC and MYC target genes when compared to cases with ≤50% positive tumor nuclei." (PMID 22511926, 2012).
tumor (continued). "Conversely, the incidence of tumor development in the liver of MYC-DDC mice was significantly attenuated by treatment with NAM (P = .038)." (PMID 23024800, 2012). "More specifically, we have found that cases of both primary and secondary DLBCL with a MYC translocation reproducibly have >50% of tumor nuclei which are strongly positive for MYC protein." (PMID 22511926, 2012). "Firstly, the results presented here demonstrated that ARF-BP1 was also highly expressed in MYC-dependent B cell lineage neoplasms of both humans and mice." (PMID 22754359, 2012). "We tested 77 cases of DLBCL and identified 15 cases with high MYC protein expression (nuclear staining in >50% of tumor cells)." (PMID 22511926, 2012). "All of the cases of primary DLBCL with a MYC rearrangement (9%; a frequency consistent with prior reports) showed MYC staining in >50% of tumor nuclei (range of 60–90%, manual scoring)." (PMID 22511926, 2012). "The MYC oncoprotein which is activated in several tumor types is significantly upregulated in MPeMSCs; MYC gene is important for stem cell proliferation and for the maintenance of pluripotent properties of stem cells." (PMID 23285196, 2012). "NF-κB can also stimulate tumor proliferation through inducing certain oncogenes such as cyclin D1 and c-MYC." (PMID 22952718, 2012). "Down-regulation of MYC protein expression leads to tumor regression in animal models, indicating that MYC proteins represent interesting therapeutic targets." (PMID 23162796, 2012). "In our group we are interested in generating c-MYC-specific T cells for specific elimination of MYC-overexpressing tumor cells." (PMID 22860051, 2012). "Necropsy of moribund BCL-XL/MYC mice showed that tumors were disseminated throughout the hematopoietic tissues with extensive involvement of spleen and bone marrow and tumor infiltration of the liver." (PMID 22393362, 2012). "We also observe a statistically significant difference in clinical outcome when we raise the cut-point for classifying tumors as MYC IHC-High to >60% positive tumor nuclei (p = 0.001, Log-rank test)." (PMID 22511926, 2012). "Rather than changing which genes are expressed, high levels of MYC increase the transcriptional output of tumor cells." (PMID 23145106, 2012). "Our detailed studies of the kinetics of tumor development showed that overexpression of MYC, either alone or together with BCL-XL or BCL-2, rapidly resulted in blast transformation of various hematopoietic cell types, including myeloid and lymphoid cells." (PMID 22393362, 2012). "Amplification of 3q26.2 including EVI1 gene and 8q24.12 including MYC oncogene were the most frequent alterations occurring in 72–75% of tumors suggesting a role for these genes in tumor maintenance or dissemination process." (PMID 22355333, 2012). "Immunohistochemical stainings of tumor cells in FLIPL/MYC mice showed similar staining patters as Mock/MYC." (PMID 22393362, 2012). "When c-MYC expression was inactivated by doxycycline administration, tumours transplanted into syngeneic mice regressed as OS cells differentiated into mature osteocytes." (PMID 23036272, 2012). "The only identifiable difference was the degree of ploidy in pre-neoplastic tissue where MYC/Rb mutant pre-tumor tissue displayed a higher degree of ploidy than MYC mutant pre-tumor tissue in hepatocyte populations." (PMID 21573126, 2011). "Taken together, c-MYC moderately enhances the anti-tumor effect of several DNA-damaging agents through sensitization to apoptosis in c-MYC over-expressing DAOY MB cells." (PMID 21324178, 2011).